LINC-ROR (long independently transcribed non-coding RNA, regulator of reprogramming)
Diseases named in the same sentence as LINC-ROR in open-access papers (continued):
Sharing a sentence is not in itself a finding about the gene and the disease.
breast carcinoma (continued). "Thus, this study might help not only in establishing a role for linc-RoR in estrogen-independent and tamoxifen resistance of ER+ breast cancer, but also suggesting a link between linc-RoR and MAPK/ERK pathway." (PMID 29041978, 2017). "Conversely, linc-ROR overexpression enhanced the EMT, migration, and invasion of breast cancer cells." (PMID 39997609, 2025). "Numerous studies have identified upregulated lincRNAs, including BREAST CANCERR4, linc-ROR, and HOX transcript antisense RNA (HOTAIR), as the key breast cancer invasion and metastasis facilitators." (PMID 39997609, 2025). "This suggests that linc-ROR acts as a regulator to influence the estrogen-independent growth (EIG) and drug resistance of breast cancer." (PMID 39408810, 2024). "E-cadherin membrane localization was impacted by the upregulation of Mucin1 (MUC1) through linc-ROR function as a ceRNA for miR-145 in triple-negative breast cancer (TNBC), increasing invasion and metastasis in a breast cancer cell line." (PMID 36827545, 2023). "Recent studies have found that LINC-ROR overexpression can trigger proliferation, EMT, progression, and metastasis via interaction with miRNAs and the TGF-β signaling pathway in breast cancer." (PMID 33745265, 2021). "We showed that overexpression of linc-ROR induced EMT, and promoted migration and invasion in breast cancer cells, while knockdown of linc-ROR in breast cancer cells repressed breast cancer lung metastasis in vivo in immunodeficiency mice." (PMID 32929060, 2020). "More importantly, the chemoresistance of pancreatic cancer (PC) and breast cancer (BC) as well as radio-resistance of colorectal cancer (CRC) cells were observed to be elevated by linc-ROR." (PMID 32850817, 2020). "linc‐ROR is important in regulating epithelial‐to‐mesenchymal transition (EMT) and can promote breast cancer progression and metastasis through the regulation of miRNAs." (PMID 32335998, 2020). "Remarkably, our previous study identified, for the first time, a novel role of linc-ROR in control of epithelial–mesenchymal transitions (EMT) and metastasis in breast cancer cells." (PMID 32929060, 2020). "Many studies have indicated that several lncRNAs, such as HOTAIR, linc-ROR, and BCAR4, are upregulated and they promote breast cancer invasion and metastasis." (PMID 32929060, 2020). "Linc-ROR functions as an important regulator of EMT and can promote breast cancer progression and metastasis through regulation of mi-205." (PMID 31214490, 2019). "We examined the importance of linc-ROR in the MCF-7 and MDA-MB-231 breast cancer cells by analyzing the proliferation and invasion of those cells in vitro." (PMID 30250400, 2018). "When linc-ROR was knocked down in the MCF-7 and MDA-MB-231 breast cancer cells, the expression levels of TGF-β were also diminished." (PMID 30250400, 2018). "We also found that the expression levels of linc-ROR affected several factors in the TGF-β pathway suggesting that the regulatory link between linc-ROR and TGF-β is potentially important for progression of advanced breast cancer." (PMID 30250400, 2018). "The regulatory action of linc-ROR can affect the activity of the TGF-β signaling pathway, which has been proven critical for mammary development and breast cancer." (PMID 30250400, 2018). "Taken together, these results suggest that linc-RoR promotes estrogen-independent growth and activation of MAPK/ERK pathway of breast cancer cells by regulating the ERK-specific phosphatase DUSP7." (PMID 29041978, 2017). "Linc-ROR also functions as an important inducer of EMT and metastasis through preventing mir-205 target genes from degradation in breast cancer." (PMID 29237490, 2017). "In this study, linc-ROR was suggested to have a role as a sponge for mir-205 thereby preventing the degradation of its targets such as ZEB1 and ZEB2 in breast cancer to regulate CD24-CD44+ EMT stem cells." (PMID 26932376, 2014).
breast carcinoma (continued). "Another study indicated that in natural tamoxifen-resistant breast cancer cells (MDA-MB-231), the downregulation of linc-ROR could inhibit EMT and enhance sensibility to tamoxifen by increasing miR-205 expression and suppressing ZEB1 and ZEB2." (PMID 36827545, 2023). "For example, lincRoR has been found to act as a competing endogenous RNA of microRNA-205, which prevented the degradation of EMT inducer ZEB2 and enhanced the aggressiveness of breast cancer cells." (PMID 36986051, 2023). "According to RT–qPCR result, we found that miR‐194‐3p was significantly downregulated in breast cancer tissues and the expression level of miR‐194‐3p was negatively correlated with linc‐ROR." (PMID 32335998, 2020). "linc‐ROR is reported to be a potential biomarker of breast cancer, but the detailed mechanism of linc‐ROR‐mediated breast cancer regulation has not been fully studied." (PMID 32335998, 2020). "Therefore, linc-ROR is an important regulator of EMT and promotes the progression and metastasis of breast cancer by regulating miRNAs." (PMID 31214490, 2019). "In this study, lncRNA ROR (linc-ROR) was examined by real-time PCR in different breast cancer cell lines and breast tumor tissues/non-tumor tissues were collected from both breast cancer patients and healthy controls." (PMID 30250400, 2018). "In this study, we identified and characterized linc-RoR as a novel regulator of MAPK/ERK signaling cascade and thereby may have critical roles in ligand-independent growth of breast cancer cells." (PMID 29041978, 2017). "Thus, linc-ROR can operate as a chief regulator of EMT and advance the progression and metastasis of breast cancer through regulation of miRNAs." (PMID 27686732, 2016). "However, studies of the role of linc‐ROR in breast cancer are not yet sufficient, especially studies of the ceRNA mechanism of linc‐ROR." (PMID 32335998, 2020). "Linc-ROR, as a new intergenic non-protein coding RNA, has been considered to be a pivotal regulatory factor that affects the occurrence and development of human tumors, including breast cancer (BC), colorectal cancer (CRC), pancreatic cancer (PC), hepatocellular carcinoma (HCC), and so on." (PMID 32850817, 2020).
hepatocellular carcinoma (42 papers, 2015 to 2025). A malignant tumor that arises from hepatocytes. "Another study demonstrated that linc-RoR is a hypoxia-responsive lncRNA that is functionally linked to hypoxia signaling in hepatocellular carcinoma through a miR-145/HIF-1α signaling module." (PMID 33407675, 2021). "It has been reported that linc-ROR is also an important regulator of human tumor occurrence and development, such as hepatocellular carcinoma and pancreatic cancer." (PMID 39408810, 2024). "Our previous study also reported that curcumin inhibited the proliferation of hepatocellular carcinoma cells by suppressing lincROR expression and inactivating Wnt/β-catenin signalling." (PMID 39546475, 2024). "Recent studies showed that lincROR was obviously up-regulated in various tumors, including colorectal cancer, breast cancer, pancreatic cancer, hepatocellular carcinoma, and lung cancer." (PMID 39546475, 2024). "One of the recent studies has indicated that lincROR contributed to the chemoresistance of hepatocellular carcinoma through Twist-mediated EMT." (PMID 36986051, 2023). "Active research is currently underway to link linc-ROR chemotherapy resistance in hepatocellular carcinoma." (PMID 36827545, 2023). "It has been divulged that LINC-ROR is overexpressed and linked to the hypoxia network via modulating miR-145-HIF-1α expression in hepatocellular cancer." (PMID 33745265, 2021). "The expression level of linc-ROR was elevated in hepatocellular carcinoma, and the sponge action of linc-ROR on miR-876-5p released FOXM1, thus forming a positive feedback loop." (PMID 33163123, 2020). "During hypoxia, hepatocellular cancer cells contained the linc-RoR (regulator of reprogramming), thus decreasing miR-145 and hypoxia-inducible factor 1 alpha (HIF-1α) in recipient cells." (PMID 30781588, 2019). "Marked upregulation of linc-ROR can be observed in various cancers, like BC, pancreatic cancer (PC), hepatocellular cancer (LC), EC, and nasopharyngeal carcinoma; furthermore, linc-ROR works as a tumor suppressor in glioma." (PMID 29596364, 2018). "Long intergenic non-coding RNA ROR (LINC-ROR) was found to be an effector molecule of chemotherapeutic drug resistance in hepatocellular cancer cells (HCC)." (PMID 29558960, 2018). "Furthermore, lincROR is involved in the resistance to doxorubicin in hepatocellular carcinoma and tumor growth in esophageal squamous cell carcinoma." (PMID 39546475, 2024). "In addition, high DEPDC1 expression mediated by LincRNA regulator of reprogramming (Linc-ROR) accelerated the development of hepatocellular carcinoma and angiogenesis." (PMID 36768316, 2023). "Similarly, linc-ROR, which is highly expressed in hepatocellular cancer cells, was also found in significant quantities in HCC-delivered extracellular vesicles and was even more abundant after sorafenib treatment." (PMID 32498257, 2020). "Similarly, ZFAS1 binds miR-150 in hepatocellular carcinoma, Linc-RoR binds miR-145 in endometrial cancer stem cells and CASC2 regulates concentration of miR-21." (PMID 27233618, 2016). "More recently, the same group demonstrated that the expression of lncRNAs linc-RoR (long intergenic non-coding RNA, regulator of reprogramming) in hepatocellular cancer is responsive to hypoxic conditions and the transfer of exosomal linc-RoR can modulate the intercellular response to hypoxia." (PMID 25338714, 2015). "Similarly, the transfer of lncRNAs (TUC339 and linc-ROR) within extracellular vesicles was described among human hepatocellular cancer cells and might contribute to disease progression and resistance to chemotherapy." (PMID 36552246, 2022). "Curcumin induced cell cycle arrest and apoptosis in hepatocellular carcinoma (HCC) by down-regulating lincROR which has been demonstrated to activate Wnt/β-catenin signaling." (PMID 33912467, 2021).
hepatocellular carcinoma (continued). "LINC-ROR, acting as a ceRNA in ESCs, is involved in the occurrence and development of different human tumors (breast cancer, colorectal cancer, pancreatic cancer, hepatocellular carcinoma), and it represents a potential biomarker with clinical significance that can be used as therapeutic target." (PMID 34439740, 2021). "In hepatocellular carcinoma cells, TGF-β1 induced the enrichment of lincRNA-ROR (linc-ROR) in extracellular vesicles, promoting the formation of spheroid CD133+ stem-like cells against sorafenib-, doxorubicin-, and camptothecin-induced cancer cell death." (PMID 35736633, 2022). "LINC-ROR sponge activity against miR-145 also leads to the derepression of ZEB2, inducing EMT in hepatocellular carcinoma and promoting metastasis." (PMID 34439740, 2021). "The upregulation of Linc-ROR and FOXM1 has been reported to impair the sensitivity of hepatocellular carcinoma cells to sorafenib." (PMID 34447693, 2021). "In endometrial cancer stem cells, linc-RoR bound miR-145 in a similar manner, and ZFAS1 bound miR-150 in hepatocellular carcinoma." (PMID 33422052, 2021). "Here, it has been demonstrated that CD90+ hepatocellular cancer cells derived from the Huh7 cell line secrete exosomes containing different types of lncRNAs, including HOTAIR, HULC, linc-ROR and H19." (PMID 26516918, 2015). "Recent study also indicates that linc-ROR contributes to TGFβ-induced acquisition of CD133+ liver CSC and chemoresistance in hepatocellular cancer, although the underlying mechanisms have not yet been fully elucidated." (PMID 29237490, 2017). "Moreover, linc-ROR functioned as a molecular sink for miR-145 to regulate the lncRNA RAD18 E3 ubiquitin-protein ligase (RAD18) expression, promoting DNA repair and radioresistance in hepatocellular cancer cell lines." (PMID 36827545, 2023). "In hepatocellular carcinoma cell lines, FOXM1 was previously observed to transcriptionally activate long intergenic non-protein coding RNA regulator of reprogramming (Linc-ROR)." (PMID 34447693, 2021).
pancreatic cancer (30 papers, 2016 to 2025). "For example, linc-ROR is not only associated with the maintenance and differentiation of pluripotent stem cells, but also plays a role in diseases such as breast and pancreatic cancer." (PMID 39408810, 2024). "Similarly, the linc-ROR expression level was significantly associated with tumor sizes and lymph node metastasis in gallbladder cancer, whereas, in pancreatic cancer, linc-ROR upregulation was related to poor prognosis." (PMID 36827545, 2023). "Loss-of-function approaches showed that linc-ROR depletion suppressed cell proliferation, cell motility, and chemoresistance in vitro and attenuated tumor growth in vivo, in line with recent evidences in other solid tumors such as breast and pancreatic cancer." (PMID 29237490, 2017). "In pancreatic cancer cells, linc‐ROR regulation of the miR‐124/PTBP1/PKM2 axis of action resulted in gemcitabine resistance in pancreatic cancer cells." (PMID 40579921, 2025). "Targeting lncRNAs, such as linc-ROR in pancreatic cancer and RMRP in bladder cancer, has led to a marked reduction in tumor volume and weight, as well as inhibited tumor metastasis in BALB/c nude mice or C57BL/6J male mice." (PMID 39925803, 2025). "The overexpression of linc-ROR in a mouse model promoted the proliferation, migration, invasion, and distant metastasis of pancreatic cancer cells." (PMID 39408810, 2024). "In vitro, LINC-ROR knockdown reduced pancreatic cancer cell proliferation, colony-forming ability, and invasion and impaired pancreatic cancer cell stem-like properties." (PMID 39170516, 2024). "The Hippo/YAP pathway was activated by linc-ROR in pancreatic cancer cell lines with increased proliferation, migration, and invasion." (PMID 36827545, 2023). "Another study with pancreatic cancer samples and cell lines demonstrated that linc-ROR activates the derepression of core transcription factor Nanog by acting as a ceRNA and becoming a sink for miR-145." (PMID 36827545, 2023). "Down-regulation of linc-ROR significantly sensitized pancreatic cancer cells to gemcitabine whereas overexpression of linc-ROR significantly reduced the sensitivity of pancreatic cancer cells to gemcitabine." (PMID 34439315, 2021). "Recent studies have demonstrated that certain lncRNAs can act as competing endogenous RNA (ceRNAs) or miRNA “sponges” to modulate chemotherapy sensitivity in pancreatic cancer, such as linc-ROR, GAS5 and linc-DYNC2H1-4." (PMID 31514732, 2019). "In pancreatic cancer, linc-ROR confers gemcitabine resistance at least partly via inducing autophagy, and further research reported a linc-ROR/miR-124/PTBP1/PKM2 axis that involved in the regulation of gemcitabine resistance in pancreatic cancer cells." (PMID 30266744, 2018). "In this study, we uncovered a critical role for linc-ROR in pancreatic cancer cell proliferation, showing that linc-ROR knockdown arrests cells at the G1 phase." (PMID 28580169, 2017). "To investigate the role of linc-ROR in pancreatic cancer, we first evaluated the linc-ROR expression in paired tumor and para-tumor tissues from 81 clinical PDAC specimens." (PMID 28580169, 2017). "Compliance with its role in iPS cells, we found that linc-ROR expression relates to stemness in pancreatic cancer cell." (PMID 28580169, 2017). "To summarize, the present work identifies linc-ROR as a novel potential oncogene in pancreatic cancer through contributing to PDAC proliferation, dedifferentiation, and stemness." (PMID 28580169, 2017). "We thus identify an important and novel regulatory mechanism of linc-ROR in pancreatic cancer progression." (PMID 28580169, 2017). "Furthermore, linc-ROR acted as an miRNA sink to several tumor suppressor miRNA members of the let-7 family in pancreatic cancer, promoting cell migration and invasion." (PMID 36827545, 2023). "In pancreatic cancer, linc-ROR promoted migration and invasion by activating the Hippo/YAP pathway, suggesting that YAP might be an underlying target to mediate EMT." (PMID 36827545, 2023).
pancreatic cancer (continued). "Additionally, lincRoR promoted cell proliferation of pancreatic cancer through the elevation of ZEB1." (PMID 36986051, 2023). "Linc-ROR was also involved in the regulation of gemcitabine sensitivity in pancreatic cancer." (PMID 34439315, 2021). "Similarly, Linc-ROR was found to induce gemcitabine resistance in pancreatic cancer cells through regulation of the miR-124/PTBP1/PKM2 axis." (PMID 30728036, 2019). "Recent studies found that Linc-ROR was upregulated in pancreatic cancer tissues and decreased Linc-ROR expression could inhibit pancreatic cancer cell proliferation, invasion, and tumourigenicity." (PMID 29549263, 2018). "Moreover, we identified an important role of linc-ROR in the maintaining of CSC properties of CSLCs in pancreatic cancer cells." (PMID 28580169, 2017). "Linc-ROR knockdown in pancreatic cancer cells inhibited cell growth and arrested in G1 phrase." (PMID 28580169, 2017). "It has been illustrated that the upregulation of LINC-ROR is associated with cell proliferation, EMT, migration, invasion, metastasis, poor prognosis, inhibition of NANOG expression, and alteration of cancer stem-like cells properties via the regulation of miRNAs in pancreatic cancer." (PMID 33745265, 2021). "In addition, linc-ROR is also a lncRNA which is up-regulated in pancreatic cancer." (PMID 34439315, 2021). "The further functional experimenters found that linc-ROR knockdown decreases pancreatic cancer cell proliferation, ability of colony formation, activity and invasion in vitro, and impaired the stem cell-like features of pancreatic cancer cell and tumorigenicity potential in vitro and in vivo." (PMID 28580169, 2017). "Several lncRNAs such as Linc-ROR, AB209630, and PVT1 have been reported to be involved in gemcitabine resistance in pancreatic cancer." (PMID 30728036, 2019). "At the same time, several lncRNAs (e.g., linc-ROR, GAS5 and linc-DYNC2H1-4) have been identified as ceRNAs to confer drug resistance in pancreatic cancer." (PMID 31514732, 2019). "In this study, we aimed to explore the role of linc-ROR in regulation of proliferation, invasion and the CSC properties of cancer stem-like cells (CSLCs) in pancreatic cancer." (PMID 28580169, 2017). "To assess the role of linc-ROR in pancreatic cancer cell proliferation, we performed MTT assays on control and linc-ROR-suppressed cells." (PMID 28580169, 2017).